MRGPRD (MAS related GPR family member D)
Description:
G protein-coupled receptor that acts as a mediator of peripheral pain and itch sensations. Activated by various ligands, such as beta-alanine, beta-aminoisobutyrate, angiotensin 1-7, alamandine and allantoin, causing a conformation change that triggers signaling via guanine nucleotide-binding proteins (G proteins) and modulates the activity of downstream effectors. MRGPRD is both coupled to G(q) and G(i) G proteins: G(q) coupling activates phospholipase C-beta, releasing diacylglycerol (DAG) and inositol 1,4,5-trisphosphate (IP3) second messengers, while G(i) coupling mediates inhibition of adenylate cyclase activity. MRGPRD is specifically expressed in neurons that innervate the epidermis and acts as a key mediator of skin stimuli, such as itch, pain and mechanical stimuli (By similarity). Required to maintain skin homeostasis in response to irritant dermatitis by initiating a signaling that promotes glutamate release, inhibiting mast cell hyperresponsiveness and skin inflammation (By similarity). Required to prevent cardiomyocyte hypertrophy following activation by alamandine, a decarboxylation product of angiotensin 1-7 (By similarity). Acts as a receptor for allantoin in dorsal root ganglion neurons, eliciting chronic itch (pruritus) (By similarity).
Synonyms: MRGD; TGR7
Tractability: Small molecule: a structure with a bound ligand is known; it belongs to a druggable protein family. Antibody: UniProt places it where antibodies can reach, with high confidence; UniProt predicts a signal peptide or a membrane-spanning region; its Gene Ontology location is reachable by antibodies, with medium confidence.
Target class: Small molecule receptor (family A GPCR); Family A G protein-coupled receptor; Membrane receptor
Gene: Protein-coding gene on chromosome 11 (68,980,021 to 68,980,986, reverse strand). Ensembl gene ENSG00000172938.
Subcellular location: Cell membrane
Pathways (Reactome):
Signal Transduction: Peptide ligand-binding receptors
Gene Ontology:
Molecular function: G protein-coupled receptor activity; protein binding; G protein-coupled peptide receptor activity
Biological process: adenylate cyclase-inhibiting G protein-coupled receptor signaling pathway; phospholipase C-activating G protein-coupled receptor signaling pathway; G protein-coupled receptor signaling pathway; negative regulation of cardiac muscle hypertrophy; sensory perception of itch; adenylate cyclase-activating G protein-coupled receptor signaling pathway; adenylate cyclase-modulating G protein-coupled receptor signaling pathway; angiotensin-mediated vasodilation involved in regulation of systemic arterial blood pressure
Cellular component: extracellular region; plasma membrane; membrane
Genetic constraint (gnomAD): Missense variants: 392 observed, 420.85 expected, observed/expected ratio (o/e) 0.93, 90% interval 0.86 to 1.01. Synonymous variants: 185 observed, 186.43 expected, observed/expected ratio (o/e) 0.99, 90% interval 0.88 to 1.12.
Homologues: Orthologues: chimpanzee MRGPRD (97% identical), macaque MRGPRD (88% identical), dog MRGPRD (61% identical), mouse Mrgprd (60% identical), rat Mrgprd (60% identical), guinea pig MRGPRD (53% identical). Paralogues in human: MRGPRX1 (38% identical), MRGPRX4 (38% identical), MRGPRX2 (37% identical), MRGPRX3 (37% identical), MRGPRF (32% identical), MAS1L (32% identical), MRGPRE (31% identical), MAS1 (31% identical), MRGPRG (30% identical), GPR152 (21% identical).
Diseases named in the same sentence as MRGPRD in open-access papers:
MRGPRD is named in the same sentence as 34 diseases in open-access papers, as found by Europe PMC text mining. Sharing a sentence is not in itself a finding about the gene and the disease. The quoted sentences say what the papers report.
lung carcinoma (2 papers, 2012 to 2021). "MRGPRD involvement is not limited to neurons and cardiovascular tissues; high expression levels of MRGPRD have also been reported in human lung cancer tissues, where it promotes cell proliferation and tumorigenicity." (PMID 34948051, 2021).
irritant dermatitis (1 paper, 2023). An inflammatory skin condition caused by direct contact between the skin and an irritating substance. "Conversely, depletion of the MrgprD+ neurons resulted in increased susceptibility to Mrgprb2-mediated irritant dermatitis suggesting that MrgprD+ neurons may be responsible for setting an overall tone of CTMC responses in the skin." (PMID 37006298, 2023).
Paresthesia (1 paper, 2023). Abnormal sensations such as tingling, pricking, or numbness of the skin with no apparent physical cause. "MrgprD is expressed in cutaneous sensory neurons in the skin, and the binding of β-alanine to MrgprD has been suggested to be responsible for the associated symptoms of paresthesia." (PMID 36839397, 2023).
bacterial infections (1 paper, 2024). "β-alanine is known to activate the NF-κB signaling pathway, which contributes to the inflammatory response, and it specifically activates G protein-coupled receptors (MrgprD) in the organism, thereby regulating inflammation triggered by bacterial infections." (PMID 39624517, 2024).
MRGPRD also shares sentences with these, for which no sentence is quoted: cancer (6 papers); Hypertension (6); tumor (5); cardiac hypertrophy (3); Cirrhosis (3); portal hypertension (3); Clear Cell Renal Cell Carcinoma (2); Metastatic Disease (2); non-small cell lung carcinoma (2); pancreatic cancer (2); pulmonary fibrosis (2); renal tumor (2); allergic contact dermatitis (1); COVID-19 (1); dilated cardiomyopathy (1); fibrosarcoma (1); heart failure (1); hypertrophy (1); hypotension (1); kidney disease (1); liver cancer (1); lung adenocarcinoma (1); osteoporosis (1); papilloma (1); pulmonary hypertension (1); renal cell carcinoma (1); renal fibrosis (1); renal oncocytomas (1); stomach cancer (1); Ventricular hypertrophy (1).